NHSL2 (NHS like 2)
Tractability: Antibody: the Human Protein Atlas places it where antibodies can reach. PROTAC: its protein half-life has been measured.
Gene: Protein-coding gene on chromosome X (71,910,845 to 72,161,750, forward strand). Ensembl gene ENSG00000204131.
Subcellular location (Human Protein Atlas): Cell Junctions; Plasma membrane; Nucleoplasm
Gene Ontology:
Molecular function: protein binding
Biological process: cell differentiation
Homologues: Orthologues: chimpanzee NHSL2 (99% identical), macaque NHSL2 (98% identical), rabbit NHSL2 (88% identical), pig NHSL2 (87% identical), dog NHSL2 (85% identical), rat Nhsl2 (85% identical), guinea pig NHSL2 (84% identical), mouse Nhsl2 (84% identical), tropical clawed frog nhsl2 (46% identical), zebrafish nhsl2 (35% identical), zebrafish si:ch73-362m14.2 (15% identical). Paralogues in human: NHS (25% identical), NHSL1 (22% identical), NHSL3 (12% identical).
Diseases named in the same sentence as NHSL2 in open-access papers:
NHSL2 is named in the same sentence as 1 disease in open-access papers, as found by Europe PMC text mining. Sharing a sentence is not in itself a finding about the gene and the disease. The quoted sentences say what the papers report.
HIV-1 infection (1 paper, 2022). The type species of lentivirus and the etiologic agent of acquired immunodeficiency syndrome (AIDS). "The top downregulated transcripts in cells from treated individuals were the transcription factor ZNF90; NHSL2, which has unknown function; and IL7R, which has been shown to play a role in CD4 T cell loss during HIV-1 infection." (PMID 36175869, 2022).